HIF1A (hypoxia inducible factor 1 subunit alpha)
Diseases named in the same sentence as HIF1A in open-access papers (continued):
Sharing a sentence is not in itself a finding about the gene and the disease.
cancer (continued). "Conversely, the inhibition of HIF-1α with sh-RNAs and lncRNAs avoids vasculogenic mimicry (a process in which cancer cells mimic endothelial cells by forming blood vessels), reducing their metastatic capabilities, and restoring E-cadherin expression in Lovo and HCT116 cells." (PMID 35741024, 2022). "Therefore, molecular pathways such as those involving HIF1α and angiogenesis are activated to ensure cancer progression and growth." (PMID 35317831, 2022). "Therefore, HIF-1α helps to cope with any damage to the mitochondria so that cancer cells evoke selective mitochondrial autophagy to maintain a healthy microenvironment." (PMID 35592530, 2022). "Overexpression of HIF-1α has been reported in most carcinomas and indicates poor patient prognosis." (PMID 35236823, 2022). "The HIF-1α inhibitor BAY 87-2243 upregulated the expression of IDH3α in BJ1 fibroblasts in co-culture with ADT carcinoma cells, suggesting us that high HIF-1α expression keeps IDH3α expression at low levels to maintain the glycolytic phenotype in co-cultured fibroblasts." (PMID 35814364, 2022). "In cancer cells, the upregulation and stabilization of HIF1α contributes to the Warburg effect." (PMID 34884872, 2021). "Moreover, it targets the AMP-activated protein kinase alpha 2 (AMPKα2) for ubiquitination and degradation, activating the mammalian target of rapamycin (mTOR)–hypoxia-inducible factor 1-alpha (HIF-1α) axis and promoting cancer progression." (PMID 34199813, 2021). "Interestingly, studies have demonstrated that activation of HIF-1α by hypoxia increases the secretion of exosomes in both cancer and non-cancer cells within the TME." (PMID 34685596, 2021). "HIF1α, overexpressed in common human cancers, is essential to this cellular adaptation." (PMID 33946771, 2021). "We determined whether clinically relevant, low‐dose tipifarnib could inhibit HIF‐1α expression and cancer aggressiveness." (PMID 33773069, 2021). "Thus, inhibiting the HIF1α pathway has been believed to be a potential therapy for cancer, as well as for hypoxia-induced diseases." (PMID 35002707, 2021). "Also, TGF-β had the same behavior as HIF1-α (respectively), so cells should avert its secretion to revert cancer proliferation." (PMID 34177892, 2021). "HIF-1α was reported to induce vasculogenic mimicry formation in several human cancer cells." (PMID 34420039, 2021). "Therefore, ROS levels are a key factor in the antitumor effects of low‐dose tipifarnib and decreased ROS levels lead to the suppression of HIF‐1α expression and cancer aggression." (PMID 33773069, 2021). "Notably, HIF-1α induces expression of a variety of immunosuppressive molecules and contributes to the regulation of PD-L1 expression on cancer cells." (PMID 34680439, 2021). "It is now accepted that HIF‐1α is the primary driving force of the metabolic reprogramming seen in cancer cells, and constitutive activation of HIF‐1α resets the metabolic phenotype of the cell towards aerobic glycolysis by stimulating the glycolytic gene‐expression program." (PMID 34841716, 2021). "Additionally, development of new technologies and strategies to investigate these finding in vivo will be a milestone achievement in assessing the role of KSHV in regulating HIF1α for continuous replication under hypoxic conditions of many types of cancers." (PMID 34279223, 2021). "In addition, major genetic and epigenetic alterations already present on the cancer cells can further increase HIF-1α activity." (PMID 34572400, 2021). "The regulatory mechanisms of HIF-1α expression via miRNAs may contribute to the detrimental effects of inhalational anaesthetics and hence worsen cancer outcomes." (PMID 33673181, 2021). "Therefore, cancer cells must take over an alternative fatty acid synthesis pathway, and HIF-1α helps them to adapt to this." (PMID 34869321, 2021).
cancer (continued). "We hypothesized that the laser-activatable O2 release of pHPFON-O2 could effectively increase intracellular oxygen concentration, downregulate HIF-1α expression, elevate X-ray-mediated ROS generation, augment DNA damage, and finally lead to cancer cell death." (PMID 33483518, 2021). "Thus, HIF1α activation enables cancer cells to generate ATP in anaerobic conditions and to regulate the intracellular pH level." (PMID 34950592, 2021). "Results showed that the introduction of exogenous NF-κB expression could efficiently downregulate TCEB1 and increase HIF-1α expression in cancer cells." (PMID 34163032, 2021). "It is notable that both HIF-1α and c-myc induce the expression of a large number of glycolytic genes upon binding to highly conserved carbohydrate response elements, boosting a feed-forward cycle that reinforces the glycolytic program in cancer cells." (PMID 33804985, 2021). "Furthermore, the interaction between PRDX1 and TLR4 in human cancer cells was shown to upregulate HIF-1α, a master regulator of adaptive responses to hypoxia that is highly expressed in NES tissues (Allen and Vázquez-Medina, 2019)." (PMID 34744798, 2021). "In order to improve or develop new therapies in PDAC, it could be important to identify a subset of patients and cancer cell subpopulations expressing and hypoxia markers for HIF-1α -interfering substances." (PMID 34885243, 2021). "Similarly, hypoxia downregulated the expression of UBE2T, a ubiquitin ligase required for FADNA repair, in several cancers in a HIF-1α-independent manner, thus enhancing their sensitivity to ICL-inducing agents such as mitomycin C (MMC)." (PMID 33796526, 2021). "miR-138 and -210 are reported to control HIF-1α expression, a key factor of cancer malignancy." (PMID 33673181, 2021). "HIF-1α, as a vital transcription factor, could regulate the proliferation, metastasis, and apoptosis of cancer cells." (PMID 33754005, 2021). "This analysis allowed us to identify potential genetic control points like NFκB and HIF1α, which could serve as potential molecular targets against cancer by modifying the macrophage phenotypes." (PMID 34177892, 2021). "In general, under hypoxic conditions, HIF-1α maintains the survival requirements of cancer cells by regulating the expression of a series of glycolytic enzymes and can also bind to the vascular endothelial cell growth factor (VEGF) gene promoter to induce VEGF expression and angiogenesis." (PMID 33996598, 2021). "In addition, it has been shown that the target for MSA is the hypoxia-inducible transcription factor 1α (HIF-1α) in cancer cells under hypoxic conditions." (PMID 34205571, 2021). "HIF-1α is widely used as a marker of poor prognosis in cancer patients." (PMID 34322597, 2021). "Hypoxia also upregulated Sphk1 mRNA expression in endothelial cells and cancer cells, and this was mediated by the transcription factors HIF-1α and HIF-2α, which can bind to one of the two hypoxia response elements (HREs) identified in the human Sphk1 promoter region." (PMID 34502385, 2021). "Moreover, HIF-1α is involved in metabolic changes occurring under pathological conditions, with most studied examples in the cancer field." (PMID 34281273, 2021). "HIF-1α can also bind to hypoxia response elements (HREs) in the promoter regions of target genes and act as a transcription factor in regulating the expression of multiple cancer-related genes." (PMID 34976998, 2021). "Finally, our findings suggest a promising beneficial effect of combining TAM with baicalein for patients with TAM‐resistant cancer and highlight HIF‐1α as an attractive target for restoring TAM sensitivity." (PMID 34841716, 2021).
cancer (continued). "HIF-1A expression in the cytoplasm or/and nucleus of cancer cells has been confirmed." (PMID 33403040, 2021). "Low levels of angiogenesis and high proliferation of cancer cells induce hypoxic conditions in the tumor microenvironment that are accompanied by an increase in expression level of hypoxia inducible factor-1α (HIF-1α) providing the conditions for cancer growth." (PMID 33921908, 2021). "Based on these findings, the activation of HIF-1α in CVD constitutes a potential pro-oncogenic element that may lead to subsequent cancer and constitutes a common therapeutic target for both diseases." (PMID 34154667, 2021). "Hyperactivate AKT, HIF1-α signaling pathway, and downregulate antigen presentation related genes to promote drug resistance and immune escaping and remodel glycolysis reprogram of cancer cells." (PMID 33868368, 2021). "Interestingly, because MRV is known to inhibit HIF-1α, infection with this virus has been evaluated as a potential treatment for cancer." (PMID 34360716, 2021). "Overexpression of HIF-1α is observed in a variety of cancers and predicts unfavorable prognosis." (PMID 34611473, 2021). "Interestingly, the oncogene c-MYC, known to interact with HIF1α to enhance glycolysis in cancer cells, was correlated to the expression of PDHK1 in our data." (PMID 33668151, 2021). "HIF1α is a key regulator of hypoxia, a phenomenon related to rapid cancer cell proliferation." (PMID 33668151, 2021). "Although both sevoflurane and desflurane provide “anti-cancer” effects through HIF-1α and MMP9 changes, the regulatory mechanisms of HIF-1α and MMP9 via miRNAs may be difference from one to the other inhalational anesthetics." (PMID 33919449, 2021). "PKM2 is overexpressed in various cancer types, and its expression is regulated by HIF-1α." (PMID 33401572, 2021). "To investigate the contributions of HIF-1α in regulating glycolysis of cancer cells under hypoxia, we evaluated the dynamics of HIF-1α protein and its target genes related to glucose metabolism, including GLUT1, HKII, LDHA, and PDK15, following prolonged hypoxia." (PMID 33637716, 2021). "A small number of hypoxia-associated genes (APLN, HIF1A, and BNIP3), cancer stem cell (CSC) markers (CD24 and CD44), hormonal regulation (HR) genes (ESR1, PGR, and TFF1), other selected genes (PPARGC1A, ILK), and HKGs (RPL32, GUSB, TBP, OAZ1 and NONO) were also included in the panel." (PMID 34206049, 2021). "Hypoxia-inducible factor 1 (HIF-1α) is a transcription factor that facilitates the adaptation of cancer cells to hypoxic conditions, and may therefore serve as a prognostic marker for late recurrence." (PMID 34736510, 2021). "Additionally, HIF-1α can cooperate with CAF-secreted TGF-β2 to induce GLI2 signaling cancer stem cells, leading to enhanced stemness and chemotherapy resistance." (PMID 33732706, 2021). "ROS may modulate cancer cell metabolism by acting as secondary messengers in the signaling pathways (NF-kB, HIF-1α) involved in cellular proliferation and metastasis." (PMID 34205678, 2021). "In human cancer cells, HIF-1α can upregulate the level of PDGF transcript." (PMID 34445528, 2021). "In these 11 cancer types, NPM1 expression is positively correlated with expression of HIF1A but not with EPAS1 which encodes HIF‐2α, in line with our data showing that NPM1 interacts only with the HIF‐1α isoform." (PMID 34388291, 2021). "The roles of HIF-1α in lipid metabolism reprogramming in cancer is under-studied." (PMID 34976805, 2021). "HIF‐1α is currently regarded as a prime target for anti‐cancer therapies." (PMID 34318593, 2021). "Melatonin exerts a marked regulatory effect on the PDK/PDC axis due to its ability to directly or indirectly inhibit HIF-1α; as a result, it determines the pyruvate metabolic profile of those cancer cells that have been investigated and perhaps other diseased cells as well." (PMID 33466614, 2021).
cancer (continued). "HIF-1α pharmacologic regulators and gene therapy tools currently developed in the field of cancer research may thus be useful in the development of multitherapy protocols in MDs, complementary to emerging strategies specific to individual MDs." (PMID 34281273, 2021). "HIF-1α is an important protein that has been shown to play an important role in cancer development." (PMID 35008634, 2021). "Moreover, three of the ‘hypoxic’ cancer types were the same as the ones exhibiting significantly high expression levels of the 67 NPM1/HIF‐1α‐dependent gene signature (namely, DLBC, GBM, and THYM)." (PMID 34388291, 2021). "However, cancer cells often exhibit HIF-1α stable expression and activation, which renders them resistant to the adverse microenvironment." (PMID 33918883, 2021). "In TARBP2high tumors, HIF-1α expression was found to be higher than that in TARBP2low tumors, thereby suggesting that TARBP2 may serve as a crucial protein regulator of HIF-1α and exhibit an oncogenic role in cancer progression." (PMID 35008634, 2021). "It is possible, therefore, that cancers could develop resistance to anti-HIF drugs targeted at HIF-1α by this and other HIF-2-dependent mechanisms." (PMID 34572020, 2021). "HIF-1α is the oxygen-dependent subunit of hypoxia inducible factor 1, which plays an important role in regulating intracellular pH, invasion, and migration of cancer cells under hypoxic conditions." (PMID 34249682, 2021). "Hypoxia has been implicated in chemoresistance through several HIF-1α dependent mechanisms, including upregulation of ABC transporters, DNA repair mechanisms, autophagy, enrichment in cancer stem cell-like properties, and protection from apoptosis and senescence." (PMID 34771673, 2021). "It was concluded that these effects may cause an over-proliferation and angiogenesis of cancer cells and PBM may cause aggressiveness of cancer through TGF-β1 and Akt/HIF-1α cascades." (PMID 33572840, 2021). "Under hypoxia, HIF1α activates downstream target genes through interacting with hypoxia-response elements, which thereby regulate proliferation, apoptosis, invasion, metastasis, angiogenesis, energy metabolism, and chemoradiotherapy resistance of cancer cells." (PMID 34178647, 2021). "In addition, many reports have demonstrated that hypoxia increased chemoresistance in cancer cells through the activation of the HIF-1α pathway." (PMID 33546453, 2021). "In addition to triggering HIF-dependent transactivation of multiple genes required for cancer invasion and metastasis, HIF-1α also plays key roles in the specification and maintenance of CSCs, whose numbers are increased by intratumoral hypoxia." (PMID 34830821, 2021). "The SENP1/HIF-1α positive feedback loop mediates hypoxia-induced stemness in cancer cells." (PMID 33746578, 2021). "The positive regulatory relationship between UBE2S and hypoxia-inducible factor 1α (HIF-1α) in cancer cells might contribute to greater proliferation, angiogenesis, and metastasis of cancer." (PMID 33810518, 2021). "Hypoxia inducible factor 1α (HIF-1α) is overexpressed in common human cancers." (PMID 34633289, 2021). "HIF1A is a crucial transcription factor induced in cancer cells in response to hypoxia." (PMID 34500819, 2021). "Therefore, the inhibition of HIF‐1α represents an attractive and promising strategy to improve cancer therapy." (PMID 33773069, 2021). "As a master regulator driving cancer progression, HIF-1α activates the transcription of a large battery of genes encoding proteins that promote multiple steps of this process, including angiogenesis, metabolism, epithelial–mesenchymal transition, and immune evasion." (PMID 34740322, 2021). "HIF1α is involved in multiple key signaling pathways in cancer progression." (PMID 34686682, 2021).
cancer (continued). "Diminished oxygen availability increases the expression of hypoxia-inducible factor 1α (HIF-1α) and other pivotal genes, including some aberrantly expressed lncRNAs, which then subsequently promote cancer cell metastasis, angiogenesis, and therapeutic resistance." (PMID 34583752, 2021). "Hyperactivation of HIF-1α plays an important role in cancer metastasis." (PMID 33925645, 2021). "Generally, HIF-1a overexpression and collagen-I deposition correlation similar to that reported here, have mainly been described in 2D cell cultures, mouse models, and tissue samples in other cancer cell types." (PMID 34885188, 2021). "Finally, kresoxim-methyl analogues have been shown to promote proteasomal degradation of HIF-1α via increased oxygen tension in cancer cells." (PMID 33466454, 2021). "As the protein level of HIF1A was reduced in cancer cells treated with RDC11, we hypothesized that RDC11 might modify the activity of PHD2." (PMID 34500819, 2021). "API targets HIF-1α in several cancers such as ovarian, prostate, and lung cancer." (PMID 34829751, 2021). "The mTOR/HIF1α/ENO1 pathway can also enhance glycolysis in other cancers." (PMID 33968941, 2021). "Hif1-α andVEGF signaling is stimulated in solid tumors resulting in cancer growth." (PMID 34113483, 2021). "Studies in cancer cells have reported significant crosstalk between AR and HIF1α." (PMID 33784295, 2021). "Moreover, there is clinical evidence to show that HIF-1α plays an important role in human cancer progression." (PMID 33921487, 2021). "Hypoxic cancer cells can be resistant to RT directly by HIF-1α signaling." (PMID 34887404, 2021). "Inhibition of HIF-1α is a strategy that has been employed to redirect cells to oxidative phosphorylation, resulting in the production of cytotoxic levels of reactive oxygen species and cancer cell apoptosis." (PMID 34867818, 2021). "The EMT can be related to the activation of HIF-1α signaling, which promotes cell motility, contributes to the nutrient metabolism of cells, and activates angiogenesis to increase the energy supply so that cancer cells can survive in a harsh environment." (PMID 34572451, 2021). "An increasing number of studies have reported that the change in the oxygen level in cancer microenvironments and the HIF1α-induced hypoxia signal transduction pathway acted as a vital regulator of EMT, which played a key role in hypoxia-induced cancer invasion and metastasis." (PMID 34178647, 2021). "HIF1α transactivates genes related to the increase of glucose uptake, glycolysis, and lactate production, including PDKs, and causes cancer cells to rely on glycolysis for energy, rather than on oxidative metabolism." (PMID 34884872, 2021). "However, HIF-1α also promotes carcinogenesis and is a prominent cancer target, and various HIF-1α inhibitors have been identified and are currently being studied for their efficacy in cancer therapy." (PMID 34026764, 2021). "Taken together, both sevoflurane and desflurane may promote cancer cell migration and proliferation by direct HIF-1α upregulation via miR-138 and -210 suppression." (PMID 33673181, 2021). "In contrast, Mint3 activates the transcriptional activity of HIF-1α in specific types of cells, such as cancer cells and macrophages, by suppressing FIH-1, and Mint3 KO mice showed no apparent abnormality, which promises less adverse effects with Mint3 inhibitors." (PMID 34621018, 2021). "Additionally, HIF1-α is mainly concentrated in the nucleus, which is where many researchers believe it can regulate gene transcription in many aspects of cancer." (PMID 34124226, 2021). "Since the increase in HIF1α mRNA level was established to indicate the reduction of the oxygen concentration in the cell, which is parallel with the elevation of the cancer cell growth rate, we measured the latter value in a C6 cell population using the xCELLigence system." (PMID 33546324, 2021). "Targeting HIF-1α therefore has promising therapeutic potential in cancer treatment." (PMID 34611473, 2021).